IL10 (interleukin 10)
Diseases named in the same sentence as IL10 in open-access papers (continued):
Sharing a sentence is not in itself a finding about the gene and the disease.
multiple sclerosis (continued). "Expanded disability status scale (EDSS) as well as multiple sclerosis severity score (MSSS) correlated with reduced ability of B cells to produce IL-10 after stimulation with MBP, indicative of diminished B-cell immune regulatory function in patients with the most severe disease." (PMID 26756931, 2016). "Reduced myelin basic protein-induced CD4+ T-cell autoreactivity in interferon-β-treated multiple sclerosis patients may be mediated by monocyte-derived interleukin-10." (PMID 25738751, 2015). "The amino-terminal domain of TyrRS (1 nM) has been reported to induce PMN migration, and human myelin basic protein (10–30 μg/ml) has been reported to induce a dose-dependent release of interferon-γ, TNF-α and IL-10 from the mononuclear cells of patients with multiple sclerosis." (PMID 25915936, 2015). "This is in line with previous reports showing that C/EBPδ is involved in the regulation of IL-6 and IL-10 after LPS stimulation, although C/EBPδ suppresses IL-10 expression in dendritic cells of the central nervous system in an animal model of multiple sclerosis." (PMID 25958220, 2015). "In addition, the administration of RSV to mice developing experimental autoimmune encephalomyelitis – an animal model of human multiple sclerosis – increases expression of IL-10 and Foxp3 in T cells, the animal model of multiple sclerosis." (PMID 26441683, 2015). "Infection with helminths have been associated with increased numbers of circulating CD4+ CD25+ FoxP3+ Tregs and of autoantigen-stimulated PBLs that produce IL-10 and TGF-β, observations that have been associated with an improved clinical course in patients with multiple sclerosis." (PMID 25410903, 2014). "Th17 cells that did not co-express IL-10 were found to have a higher pathogenic potential in the mouse model of multiple sclerosis than Th17 cells that expressed IL-10." (PMID 19852819, 2009). "Thus, anti-CD20 therapies, which spare plasma cells but deplete B lymphocytes, are indeed extremely effective in treating multiple sclerosis and, interestingly, the immunosuppressive cytokine IL-10 produced by plasma cells has a protective value when present in multiple sclerosis lesions." (PMID 39045667, 2024). "In addition, through GABA-mediated pathways homotaurine has anti-inflammatory and therapeutic properties in a multiple sclerosis animal model, even involving increased IL-10-secreting responses, but unfortunately IL-18 and IL-33 cytokines have not been evaluated in that context." (PMID 35515001, 2022). "In addition, we show for the first time that B cells from multiple sclerosis patients treated with alemtuzumab have increased anti-proliferative function, that this correlates with IL-10 secretion, and that increases in regulatory B cells correlate with increases in regulatory T cells." (PMID 34777337, 2021). "For instance, a study had shown that IL-10+ Bregs could mainly regulate the initiation phase of the disease, while Tregs could cooperatively inhibit late-phase via covering IL-10+ Bregs in an experimental autoimmune encephalomyelitis (EAE) model of multiple sclerosis (MS) disease." (PMID 33198645, 2020). "Interestingly, it was shown that patients with multiple sclerosis (MS), who were co-infected with helminths had increased frequencies of IL-10-producing CD19+CD1dhigh B cells which suppressed T cell proliferation and IFN-γ production leading to a better clinical outcome in regards to MS." (PMID 31120872, 2019). "IL-10 is an anti-inflammatory cytokine that exhibits neuroprotective effects based on studies reporting that exogenous administration of IL-10 protects the brains from ischemic injury and increased severity of brain injury in IL-10 knockout mice suffering from multiple sclerosis." (PMID 28778220, 2017).
multiple sclerosis (continued). "IL-10 was also shown to be elevated in the injured adult brain in several neurodegenerative diseases and animal models of disease, such as excitotoxic shock, multiple sclerosis, EAE, middle cerebral artery occlusion, traumatic brain injury, Alzheimer’s disease and Parkinson’s disease." (PMID 27881137, 2016). "Consistent with IL-10's role in suppressing inflammation, immunization of IL-10 deficient mice with myelin antigens resulted in enhanced neuroinflammation with loss of recovery from experimental autoimmune encephalomyelitis (EAE), a mouse model for human multiple sclerosis (MS)." (PMID 22969768, 2012). "In fact, IL-4, IL-10, and IL-13 high levels promote enhanced axonal regeneration, promote neuroprotection after SCI, and reduce demyelination in multiple sclerosis." (PMID 31186006, 2019). "However, multiple sclerosis patients and healthy subjects from whom blood samples were obtained were not adjusted to age, sex, and other relevant parameters that could bias our observation on the differential IL-10 response." (PMID 30792716, 2019). "Studies in the animal model of multiple sclerosis, EAE, have shown that CD40 ablation or stimulation regulates IL-10-producing B cell number and function." (PMID 29361022, 2018). "In agreement with previous findings in a mouse model of multiple sclerosis, our results therefore suggest that dysregulation of CD163, CD206 and IL-10 impacts the resolution of organ-specific inflammation." (PMID 29324769, 2018). "Assessing 15 representative signature genes in patients with multiple sclerosis, we find that TH1/17 cells have elevated expression of CXCR3 and reduced expression of IFNG, CCL3, CLL4, GZMB, and IL10 compared to healthy controls." (PMID 29150604, 2017). "For example, in a model of multiple sclerosis, it is demonstrated that BDNF decreases TNF-α expression and upregulates IL-10 expression, an anti-inflammatory cytokine." (PMID 23912236, 2013). "In CD4 cells, PGJ2 and the TZD ciglitazone reduced IL4 production and in EAE, the animal model of Multiple Sclerosis, PGJ2 blocked splenic T cell production of IL10 and IL4." (PMID 17207275, 2007). "In multiple sclerosis, heightened TLR2/4/9 signaling agents that inhibit pyrimidine synthesis may increase IL-10 and reduce antimycobacterial immunity." (PMID 41892000, 2026). "In Multiple Sclerosis (MS), CBD in preclinical models of MS resulted in a reduction of proinflammatory cytokines such as IL-17A, IFN-γ, TNF-α, IL-6 and IL-1b and an increase in anti-inflammatory cytokines such as IL-4, IL-10 and TGF-β." (PMID 38601151, 2024). "However, in an animal model of multiple sclerosis, BDNF promotes IL-10 that reduces clinical severity." (PMID 34109176, 2021). "Likewise, in an animal model of multiple sclerosis, increasing endocannabinoid tone with UCM-707—an AEA uptake inhibitor—resulted in a significant reduction of IL-1β levels and an increase in IL-10 levels." (PMID 34685523, 2021). "The number of BTLA-expressing B cells and CD19+/BTLA+/IL-10+ cells obviously decreased in multiple sclerosis (MS) cases, while the remission of fingolimod-induced relapsed-remitted MS is related to a significantly increased number of CD19+/BTLA+/IL-10+ B lymphocytes." (PMID 33859648, 2021). "P. distasonis appeared also significantly reduced in multiple sclerosis (MS) in human patients and exposing PBMCs from healthy donor to P. distasonis extracts significantly increased the percentage of CD25+ IL-10+ T lymphocytes, including IL-10+ Tr1 regulatory (Treg) cells." (PMID 32947881, 2020). "In an animal model of multiple sclerosis, it was shown that MSC-EVs contribute to inhibit auto-reactive lymphocyte proliferation and increase the secretion of anti-inflammatory cytokines, such as IL-10 and TGF-β, to reduce the effects of multiple sclerosis." (PMID 30923617, 2019).
multiple sclerosis (continued). "While IL-10 levels were increased in the co-cultures of tolDC from healthy individuals, they were not increased in the co-cultures of tolDC from multiple sclerosis individuals." (PMID 30792716, 2019). "Daily vitamin D3 supplementation for 3 months in patients with multiple sclerosis did result in an increased proportion of CD4+IL-10+ Tregs, but these were also circulating cells and not site specific." (PMID 24943330, 2014). "Also, higher number of samples would be needed for the determination of the statistical correlation between the levels of cell proliferation and IL-10 or IFN-γ production within groups of healthy subjects and multiple sclerosis patients, as well as between these two groups." (PMID 30792716, 2019). "Interestingly, there was a difference in IL-10 production in the co-cultures of tolDC with PBMC, depending on the source of DC, i.e., whether the cells were obtained from healthy or multiple sclerosis individuals." (PMID 30792716, 2019). "While B cell-mediated immunosuppression by secretion of the anti-inflammatory cytokine interleukin-10 (IL-10) has received much recent attention, there are several reports of suppressive effects of B cells independent of IL-10, including in mouse models of type 1 diabetes and multiple sclerosis." (PMID 23940537, 2013). "By blocking the TNF-α molecule itself, for example, with infliximab, any autocrine upregulation of IL-10 as a result of TNF-α binding might be lost, disrupting the proinflammatory/anti-inflammatory balance, and may explain the adverse events in patients with multiple sclerosis." (PMID 27747245, 2016). "The author showed that after 8 weeks of vitamin D treatment, the levels of IL-10 significantly increased, while there was no significant change in the level of TGF-β1 in multiple sclerosis patients." (PMID 37681199, 2023). "CD4 Stat−/− mice do not develop EAE (a mouse model of multiple sclerosis) or EAU (autoimmune experimental uveoretinitis), have impaired Th17 cell differentiation and an increase in T cells expressing Foxp3, IL-10, IL-4 and IFNγ." (PMID 33271810, 2020).
colorectal cancer (154 papers, 2006 to 2026). A primary or metastatic malignant neoplasm that affects the colon or rectum. "For example, IFN-I signaling regulates IL-10 production by tumor-associated regulatory T cells in colorectal cancer." (PMID 40964309, 2025). "It has demonstrated both an ability to suppress intestinal inflammation (IL-10) and an increased risk of colorectal cancer." (PMID 38690367, 2024). "IL-10 promotes Wnt5a-induced M2 polarization of tumor-associated macrophages, promoting the progression of colorectal cancer." (PMID 37341987, 2023). "Its main role is to limit inflammation and maintain intestinal immune homeostasis, and IL-10-deficient mice can spontaneously form colorectal cancer when they are infected with intestinal bacteria." (PMID 35739900, 2022). "CD169+ monocytes were previously reported to be highly increased in the circulation of patients with colorectal carcinoma, to produce high amount of IL-10, and were associated with tumor-infiltrating CD169+ monocytes/macrophages and poor prognosis." (PMID 34394090, 2021). "IL-10 and IL-22 are tightly associated with the prevention of mucosal inflammation and have a variety of functions in colorectal cancer development." (PMID 32670290, 2020). "In a different study of IL-10 polymorphisms were seen in correlation with diet and colorectal cancer (CRC)." (PMID 32397555, 2020). "Epigenetic changes, such as abnormal DNA methylation of IL-10, are also closely associated with the development and progression of colorectal cancer." (PMID 32582189, 2020). "IL-10 expression has been shown to associate with improved survival rates of patients with colorectal cancer and BC, but with poor survival in non-small cell lung cancer and gastric cancer." (PMID 29256156, 2018). "For instance, we found that IL-10 -592A/C polymorphism was associated with a decreased colorectal cancer risk." (PMID 28977953, 2017). "Recently, the association between the IL-10 rs180086 polymorphism and various cancers has been reported widely, including esophageal cancer, oral cancer, gastric cancer and colorectal cancer." (PMID 29029504, 2017). "For three studied polymorphisms in IL-10 gene associated with colorectal cancer and hepatocellular carcinoma, influential analyses confirmed the overall changes in direction and magnitude under both allelic and dominant models." (PMID 27489033, 2016). "This meta-analysis was designed to examine the association of three promoter polymorphisms (−592C > A, −819C > T and −1082G > A) in IL-10 gene with the risk for colorectal cancer and hepatocellular carcinoma." (PMID 27489033, 2016). "These genomic damages induced by E. faecalis provide evidence that links bystander effect to the development of cancer, as colonized IL-10 knockout mice are susceptible to colorectal cancer." (PMID 24116215, 2013). "Carriers of the low-activity-associated IL10 C-592A variant allele eating <17.0 g of fibre per day had a significantly higher risk of colorectal cancer compared with reference group." (PMID 23216531, 2013). "In colorectal cancer, IL-10 promotes tumor growth and metastasis by inducing M2 polarization of TAMs, indicating that the M2 subtype is associated with poor prognosis in colorectal cancer." (PMID 40131539, 2025). "On the one hand, they can significantly inhibit NF-κ B/p65 signaling pathway activity, thereby down-regulating IL-6, TNF-α and IL-1β and up-regulating IL-10 in the serum of patients with colorectal cancer, which further reduces the inflammatory response associated with colorectal cancer." (PMID 40520902, 2025). "This includes histone deacetylases (HDAC) inhibition, increased expression of the transcription factor forkhead box P3 (FoxP3) specific to regulatory T cells (Tregs), and the anti-inflammatory cytokine IL-10, which help mitigate inflammation associated with colorectal cancer." (PMID 39770115, 2024).
colorectal cancer (continued). "In addition, IL-10 has been suggested as a prognostic marker of recurrence after the treatment of colorectal cancer and seems to be associated with poor prognosis." (PMID 35410210, 2022). "It is of interest that some studies have implicated STING-induced IL-10 as having an inhibitory effect on anti-tumour immunity and in some cases, a protective effect to avoid continued inflammation and development of colorectal cancer." (PMID 35281062, 2022). "For example, low doses of an adenovirus expressing the IL-12 gene mediated a potent anti-tumor effect against subcutaneous colorectal carcinomas in mice in an immunosuppressive environment; this is caused by a direct effect on Treg cells, inhibiting in vitro secretion of IL-10 and TGF-β." (PMID 32674255, 2020). "The role of colibactin-encoding E. coli has been explored in human colorectal cancer and investigated in different types of mouse models including IL10−/− mice treated with azoxymethane (AOM), C57BL/6J-ApcMin/J mice treated with AOM and dextran sodium sulfate (DSS), and nude mice with xenografts." (PMID 29225701, 2017). "The rs1800871 is a polymorphism of IL10 gene and has been associated with colorectal cancer risk." (PMID 28938543, 2017). "Our findings collectively suggest that the −592C > A polymorphism in IL-10 gene might be a susceptibility locus for colorectal cancer in East Asians." (PMID 27489033, 2016). "Taken together, we in an updated meta-analysis of three promoter polymorphisms in IL-10 gene found that the -592C > A polymorphism might be a susceptibility locus for colorectal cancer in East Asians." (PMID 27489033, 2016). "Through a comprehensive meta-analysis of three promoter polymorphisms in IL-10 gene with colorectal cancer and hepatocellular carcinoma, we found that the −592C > A polymorphism might be a susceptibility locus for colorectal cancer in East Asians." (PMID 27489033, 2016). "Given accumulating data afterwards, we decided to conduct an updated meta-analysis on the association of three promoter polymorphisms in IL-10 gene with the risk of having colorectal cancer and hepatocellular carcinoma among 5933 cases and 9724 controls from 25 articles published in English." (PMID 27489033, 2016). "Compared with healthy individuals, colorectal cancer patients have significantly higher IL-10 concentrations but individuals with adenomas do not, suggesting that IL-10 may be a better risk indicator for more advanced tumour stages." (PMID 20924374, 2010). "In colorectal cancer, M2 macrophages promote tumor progression by secreting multiple immunosuppressive factors, including IL-10, TGF-β and arginase, which suppress cytotoxic T cell activity and enhance regulatory T cell expansion." (PMID 41573553, 2025). "Wnt5a triggered the M2 polarization of tumor-associated macrophages by modifying CaKMII-ERK1/2-STAT3-mediated IL-10 production, leading to the induction of tumor growth and the metastasis of colorectal cancer." (PMID 40427533, 2025). "IL-10 is generally considered an anti-inflammatory cytokine that regulates inflammation and immune responses, offering potential antitumor effects in colorectal cancer." (PMID 40292300, 2025). "In ovarian and colorectal cancers, sustained MyD88 activation promotes increased secretion of IL-10 and TGF-β, which suppresses effector T cell function and expands Tregs." (PMID 41488647, 2025). "Previous studies have reported significantly lower serum IL-10 levels in colorectal cancer patients compared with healthy controls, which is consistent with our findings." (PMID 41267807, 2025). "It has been shown to be enriched in healthy individuals compared to colorectal cancer patients and has demonstrated anti-inflammatory effects, including the induction of interleukin-10 (IL-10)." (PMID 40958777, 2025). "Clinically, patients with colorectal cancer exposed to oxaliplatin exhibited downregulation of peripheral CD45+IL-10+ cells." (PMID 38400752, 2024).